KRAS (KRas proto-oncogene, GTPase)
Diseases named in the same sentence as KRAS in open-access papers (continued):
Sharing a sentence is not in itself a finding about the gene and the disease.
cancer (continued). "These important achievements based on synthetic lethality encouraged us to perform a chemical screening in the hope of developing efficacious clinical regimens to benefit patients with KRAS-driven cancers." (PMID 27793187, 2016). "We further assessed the impact of SAHA, a histone deacetylase inhibitor, on KRAS-mutant cancer cells." (PMID 27193833, 2016). "Crucial cancer-causing genes were identified from the fused network, including AKT, KRAS, fibroblast growth factor receptors, anaplastic lymphoma kinase, and ERBBs." (PMID 27535739, 2016). "Gene editing techniques were used to introduce KRAS mutations into some of the normal organoids grown from healthy tissue, and into cancer organoids grown from tumors that had a normal copy of the KRAS gene." (PMID 27845624, 2016). "Currently, efforts are underway to screen large panels of cancer cell lines that are more representative of the heterogeneity that exists in human KRAS-mutant cancers." (PMID 27096871, 2016). "In this study, we found that a small non-coding RNA, XPi2, altered the formation of KRAS DNA G-quadruplex and influenced cancer cell behavior." (PMID 27880931, 2016). "Taken together, these results suggest the role of OTUB1 up‐regulation in promoting cancer development in wt KRAS lung tumors." (PMID 26881969, 2016). "KRAS codon 12 mutations were present in 11 samples, and the gene had high ONC scores in both ER+ and ER− cancers (ER+: 89%, 0.5%, ER−: 60%, 0.8%)." (PMID 27161491, 2016). "We first illustrated the effect of individual hotspot mutations in BRAF, KRAS and NRAS on the sensitivity of cancer cells treated by MEK inhibitors (PD-0325901 and AZD6244)." (PMID 27356755, 2016). "Inflammatory cytokine levels such as those of IL-6 and TNF-α were significantly increased in KRAS-induced ascites, suggesting that inflammation plays a central role in KRAS-induced cancer progression." (PMID 27483433, 2016). "Based on our previous finding that Sirt2-/- mice develop spontaneous tumors, and a recent study showing that KRAS is acetylated in cancer cells, we aimed to determine the role of SIRT2 in KRAS-induced tumorigenesis in vivo." (PMID 27637077, 2016). "While for lung samples the c.34G > T substitution was the most common, in the remaining two cancer types the most common KRAS driver substitution was c.35G > A." (PMID 26902163, 2016). "The results showed that total depletion of P21 led to a complete rescue of G2/M arrest mediated by the drug pair only in KRAS-mutant cancer cells, suggesting that P21 was unambiguously necessary for the combinatorial action." (PMID 27793187, 2016). "Thus, our results – arising from three independent methods – question the proposal that anti-mitotic drugs may preferentially kill KRAS-mutant cancer cells, and caution against the use of KRAS mutational status alone as a predictive marker for patient stratification." (PMID 27412232, 2016). "Activation of these functional networks is consistent with the KRas-driven malignant transformation involving activation of signaling cascades implicated in cell migration, invasion, EMT, and KRas and cancer stem cells regulation." (PMID 27894102, 2016). "Our study demonstrated the clinical feasibility of exploring a synthetic lethal regimen of the combined inhibition of PLK1 and ROCK to defeat KRAS-mutant cancer through a mechanism that involves activation of tumor suppressor P21." (PMID 27793187, 2016). "While such inhibitors are in early stages of development, insertions into the switch 2 domain that reduce drug binding while retaining oncogenic activity are a potential mechanism of acquired resistance in KRAS mutant cancers." (PMID 26854029, 2016).
cancer (continued). "Next, we extensively investigated the effects of combined inhibition of the PLK1 and Rho signalling pathways on KRAS-mutant cancers in vitro and in vivo." (PMID 27193833, 2016). "To confirm the significant role of p21 in the efficacy of BI-2536/fasudil, we silenced p21 expression by RNAi and the CRISPR/CAS9 system, and analysed its effects on the cell cycle progression in KRAS-mutant cancer cells." (PMID 27193833, 2016). "Using RNA interference (RNAi) to suppress KRAS expression has been validated as therapeutic strategy in RAS mutant-driven mouse models of cancer." (PMID 27096871, 2016). "More recently, FADD expression and phosphorylation were reported to be pro-tumorigenic in oncogenic KRAS-driven cancers." (PMID 27556297, 2016). "In our combinatorial screening, combined PLK1/ROCK inhibition with BI-2536 and fasudil emerged as a top hit and exhibited a strong ability to induce apoptosis and cell cycle arrest in KRAS-mutant cancer cell lines." (PMID 27193833, 2016). "Several synthetic lethality screens have been performed on KRAS mutant cancer cell lines to determine potential targets, and results have frequently included genes important in cell cycle progression or mitosis, such as CDK1, cyclin A2, PLK1, and CDC6." (PMID 27167191, 2016). "These molecules have already been proposed as viable targets in the context of immunotherapeutic approaches for KRas-driven cancers." (PMID 27894102, 2016). "The CI values were all <0.7, indicating a strongly synergistic interaction between BI-2536 and fasudil in KRAS-mutant cancer cells." (PMID 27193833, 2016). "It is important to note that both types of substitutions are likely subject to positive selection, as all KRAS codon 12 and 13 non-synonymous substitutions are known to be cancer drivers." (PMID 26902163, 2016). "In summary, we developed a combinatorial drug screening based on synthetic lethality to identify novel combination partners for the treatment of KRAS-driven cancers." (PMID 27193833, 2016). "Other notable hub genes have also been claimed to be associated with cancers, including MAPK1, MAPK3, JAK2, EGFR, KRAS and NRAS." (PMID 27467251, 2016). "Recent advancements in the field and studies of the clinical relevance of KRAS as an oncogenic driver in human cancer pathogenesis, and as a therapeutic target, are reviewed." (PMID 27102293, 2016). "In both subgroups, there are rare cancer-promoting mutations predicted to activate the PI3K pathway (HRAS, KRAS, PIK3CA, PTEN, and TSC1) and to inactivate the Notch pathway (Notch1 and Notch2)." (PMID 26655088, 2016). "Inhibitors of synthetic lethal genes contributed to over 70% of the synergies observed (right), indicating that synthetic lethal genes play an indispensable role in the growth of KRAS-mutant cancers and represent applicable targets for treatment." (PMID 27193833, 2016). "This is in agreement with the active role of KRas signaling in actin nucleation and cancer cells invasion, and critical role of actin in formation of cellular protrusions." (PMID 27894102, 2016). "As expected, knockdown of p21 led to a significant attenuation of BI-2536/fasudil-induced G2/M arrest, while total depletion of p21 led to a complete rescue of G2/M arrest mediated by the drug pair in KRAS-mutant cancer cells." (PMID 27193833, 2016). "In this study, we conducted a synthetic lethal chemical screening and a combinatorial strategy to identify novel drug pairs that would effectively kill KRAS-mutant cancers." (PMID 27193833, 2016). "Other examples with different oncolytic viruses also link oncogenic KRAS mutations, which are initiating mutations in PDAC, to downregulation of ISGs in multiple cancer types." (PMID 27533247, 2016).
cancer (continued). "Orthologs of these viral oncogenes were then found in transforming DNA fragments in human cancers in the form of mutated versions of the HRAS and KRAS proto-oncogenes." (PMID 27102293, 2016). "The RAS genes, KRAS, HRAS, and NRAS, are the most frequently mutated proto-oncogenes in human cancers in the United States and are responsible for 43% of all cancer deaths." (PMID 27684555, 2016). "As a principal isoform of three RAS genes, KRAS is the “black sheep” in this family, and cancers related to mutations in KRAS (KRAS4A and KRAS4B) alone account for approximately one million deaths per year." (PMID 27793187, 2016). "As opposed to this, it has been reported that combined inhibition of anti-apoptotic BCL2 family members and effectors of the RAS pathway can effectively induce cell death in KRAS mutant cancers." (PMID 27845624, 2016). "A study in KRAS mutant cancers, which have high TRAIL-R2 expression, found that stimulation of TRAIL signalling in fact promoted cancer progression, invasion and metastasis." (PMID 27140313, 2016). "Overall, these results indicate that BI-2536/fasudil has substantial preclinical in vivo efficacy in different types of KRAS-mutant cancer models and provide a rationale for this combination in clinical trials." (PMID 27193833, 2016). "The change of the KRAS protein, which was the prime therapeutic target for diverse human cancers, will induce the alteration of many key molecules of downstream signaling pathways including Ras-Ral-CDC42." (PMID 27769041, 2016). "We searched Pubmed, MEDLINE, EMBASE, and the Cochrane Library databases for articles including following terms in their titles, abstracts, or keywords: ‘ampullary or periampullary or ampulla of vater’, ‘cancer or carcinoma’, and ‘KRAS’." (PMID 27517148, 2016). "Approximately one third of human cancers have an activating mutation in one of the three RAS genes; HRAS, NRAS, or KRAS." (PMID 27911940, 2016). "Our results show that dual inhibition of polo-like kinase 1 and RhoA/Rho kinase (ROCK) leads to the synergistic effects in KRAS-mutant cancers." (PMID 27193833, 2016). "The present investigation begins to address the basic shortage of viable targets on the surface of cancer cells expressing KRas mutants." (PMID 27894102, 2016). "An array of trans-regulatory factors - RBPs and miRNAs - known to regulate KRAS are often misexpressed in various types of cancer." (PMID 26930719, 2016). "Treatment of KRAS-positive cancer cell lines with AI II effectively reduces, in a dose-dependent manner, cell growth, as well as the ability to form colonies under adherent conditions." (PMID 26842935, 2016). "Since then, our understanding of the role of constitutively activated KRas signaling in tumorigenesis and cancer cell biology has significantly increased." (PMID 27894102, 2016). "Here the authors describe the activity of Deltazinone 1, a new highly selective PDEδ inhibitor of KRAS-dependent cancer cell growth with low cytotoxic side effects." (PMID 27094677, 2016). "Retrospective analysis of response rate by KRAS mutational status resulted in 70% of a partial or complete response in KRAS wild-type cancers; meanwhile, there was 41% of ORR in cancers with KRAS mutation (OR 3.42, 1.35–8.66; p = 0.008)." (PMID 27127793, 2016). "Restoration of BIM expression was shown to resensitize KRAS-mutant human and mouse cancer cells to combined PI3K and MEK inhibition, implying a role for targeting specific apoptotic mediators in addition to PI3K and MEK." (PMID 27765909, 2016). "Mutations in KRAS are frequently reported in pancreatic and many other cancers; thus, KRAS is an attractive therapeutic target." (PMID 27322423, 2016).
cancer (continued). "Starting from the cancer genes KRAS, NRAS and HRAS (that we will name RAS trio), similar in structure and mutational profile, we seek to extend this conservation to all the Ras superfamily members (in total, 133 different proteins belonging to the PF00071)." (PMID 26860319, 2016). "In this review, the most promising paths taken in an attempt to suppress the effects of KRAS in cancer are discussed." (PMID 27096871, 2016). "Utilizing the heterogeneous cytospins, KRAS and BRAF gene mutational status from xMD-dissected cancer cells was compared to manual macrodissected cytospin slides by pyrosequencing." (PMID 26999048, 2016). "On the basis of the broad efficacy of combined PLK1 and ROCK inhibition against KRAS-mutant cells in vitro, we assessed the therapeutic efficacy of this combination in a series of preclinical cancer models in vivo." (PMID 27193833, 2016). "Taken together, these results suggest that KRAS-mutant cancer cell lines expressing high levels of MYC are especially sensitive to microtubule-interfering agents, opening up new avenues for therapeutic intervention." (PMID 27412232, 2016). "Decades of research have shaped our understanding of the biochemistry, structure, and cellular signaling of KRAS in cancer." (PMID 27096871, 2016). "Hotspot missense mutations on known cancer genes such as ERBB2 and KRAS were largely observed as region-specific aberrations." (PMID 27175599, 2016). "Mutated KRAS induces GLUT1 and stem cell-like properties in human cancer linked to ALDH1A1 expression." (PMID 27863474, 2016). "Among these, five novel mutations in cancer-related genes (KDR, STK11, MLH1, KRAS, and PTPN11) were detected in ES, and these mutations were confirmed with traditional Sanger sequencing." (PMID 27077911, 2016). "For example, activating mutations in the KRAS gene prevail in lung, colon and pancreatic cancers, while mutations in NRAS and HRAS are rarely found in these cancer types." (PMID 26799184, 2016). "We observed that KRAS mutant cancer cell lines (HCT116 and H460) and MDA-MB-435, with a high GSTO1 expression, were sensitive to GSTO1 knockdown, but not MCF7 cells." (PMID 27703239, 2016). "Taken together, these results suggest that this novel drug pair can rather effectively inhibit the growth of a large proportion of KRAS-mutant cancer cells of different tissue origins." (PMID 27193833, 2016). "Alternative means of blocking KRAS, such as synthetic lethal approaches or combined inhibition of important downstream pathways, are being pursued to treat these cancers." (PMID 26859456, 2016). "Our study revealed a preclinical rationale for exploring a synthetic lethal regimen that combined the inhibition of PLK1 and Rho signalling to conquer KRAS-mutant cancer." (PMID 27193833, 2016). "As an example, constitutive activation of RAS signaling, particularly KRAS, is known to be the oncogenic driver for approximately 20 % of all human cancers." (PMID 27686855, 2016). "The observed S6K inhibition at a high pimasertib dose (> 0.32 μM) on day 1 agreed with our previous finding of mTOR upregulation via ERK-dependent transcription in KRAS-mutant cancer cells." (PMID 27102436, 2016). "First, KRAS is the most potent of the gain-of-function oncogenes, since it drives more human cancers than any other." (PMID 27684555, 2016). "To further confirm that KRAS activity is important for the regulation of S100A10 expression in cancer cells derived from human tumors, we depleted KRAS from A549 and MiaPaca2 cells." (PMID 27351226, 2016). "For this purpose, we analysed a panel of KRAS-mutant cancer cell lines for their response to a 48-hour treatment with STLC." (PMID 27412232, 2016).
cancer (continued). "Because both compounds have been already tested in humans, they provide excellent candidates for validating the concept of dual inhibition of MEK and ERBB2 in more advanced models of KRAS-mutant cancer." (PMID 26018524, 2015). "In cultured cells, wild-type HRAS, NRAS or KRAS have been shown to promote proliferation of oncogenic RAS-driven cancer cell lines by mediating EGF signaling." (PMID 25902334, 2015). "These animals develop pre-cancerous lesions and eventually malignant tumors in the pancreas due to organ-specific expression of a constitutively active KRAS small GTPase, thereby closely mimicking the human pathology." (PMID 26070712, 2015). "Subsequently, in 1994, cancer-specific DNA mutations in NRAS (myelodysplastic syndrome 7) and KRAS (pancreatic cancer 8) were detected in the blood of cancer patients." (PMID 26119132, 2015). "The mutations in the oncogenes KRAS and CCND1 genes are well-established oncogenic mutations in other cancer types." (PMID 26415226, 2015). "In the pancreatic tumor microenvironment, KRAS mutant cancer cells induced the expression of GLI1 in surrounding fibroblasts, followed by the binding of GLI1 to the cytokine interleukin (IL)-6 promoter inducing its expression." (PMID 26633513, 2015). "Other NGS liquid biopsy methods such as CAPP-Seq reported 96% specificity and although SafeSeqS reported 99.2% specificity this latter method was only tested on a single gene, KRAS, in a single cancer (colorectal)." (PMID 26474073, 2015). "This study implicated both known (KRAS, MYCN and TPD52) and novel (CCT6A, IGFBP3 and SALL2) cancer genes in TGCT pathogenesis." (PMID 25303610, 2015). "Our data also imply that the survivors that remain are those rare cells in the population that stochastically move away from dependency on the KRAS activity and gain a growth advantage when the cancer is targeted by the drug combination." (PMID 26158412, 2015). "ME1 expression was found to be mutant KRAS associated in both a NSCLC mouse model and human NSCLC cancer cell lines." (PMID 26173780, 2015). "EGFR, HER2, KRAS, PTEN and PI3K were sequenced for cancer-associated mutations; in addition, HER2 and EGFR copy numbers or EML4-ALK (echinoderm microtubule-associated protein-like 4–anaplastic lymphoma kinase) rearrangement were evaluated by FISH." (PMID 26247735, 2015). "Both KRAS isoforms, therefore, should be taken into account in developing effective cancer therapies." (PMID 26715448, 2015). "Members of the MAPK signalling pathway, such as NRAS, KRAS and BRAF are among the most frequently mutated proto-oncogenes in cancer." (PMID 26090869, 2015). "It is important to note that even responders to anti-EGFR therapy routinely develop secondary resistance during anti-EGFR therapy, often by selection of KRAS/NRAS or BRAF-mutant clones arising from a RAS-wildtype cancer." (PMID 26299805, 2015). "RAS and RAF gene mutations have been considered potential markers of sensitivity to MEK inhibition largely due to the constitutive activation of MEK seen in BRAF mutant cancer cells and to a lesser extent in KRAS mutant cells." (PMID 26404261, 2015). "The same synergistic interaction was observed in xenografts, autochthonous KRAS-driven lung adenocarcinomas in mice, and tumor cells isolated from cancer patients." (PMID 26295265, 2015).